FAM107A (family with sequence similarity 107 member A)
Diseases named in the same sentence as FAM107A in open-access papers (continued):
Sharing a sentence is not in itself a finding about the gene and the disease.
tumor (25 papers, 2009 to 2026). "Our analysis showed a low mutation frequency (0.9%) of FAM107A in tumor cases from TCGA with deep deletion as the main type of FAM107A genetic alteration." (PMID 35669436, 2022). "The FAM107A expression is reduced in most cancers, and its down-regulated expression was linked to poor overall survival and progression-free survival of tumor patients." (PMID 35669436, 2022). "Their results showed that IQGAP3/BMP4 overexpression was observed in higher-stage and higher-grade diseases with high risks of recurrence and progression, whereas IQGAP3/FAM107A overexpression was associated with larger tumor size and disease progression." (PMID 33672869, 2021). "To study further the potential mechanisms underlying FAM107A downregulation we have analyzed the DNA methylation level of this gene in 15 cell lines, 21 primary tumors and 8 non-tumor controls." (PMID 28710449, 2017). "In addition, the correlation between FAM107A expression and tumor mutational burden (TMB)/microsatellite instability (MSI) was analyzed across all cancers of TCGA." (PMID 35669436, 2022). "In DU145 and PC-3 cells, FAM107A OE inhibited cell proliferation, migration, invasion, and tumor formation, while promoting apoptosis." (PMID 41008642, 2025). "Collectively, these finding support a tumor suppressor role for both FAM107A and TWIST2 in PCa, with their methylation statuses serving as potential prognostic biomarkers." (PMID 41008642, 2025). "Among the candidate genes, we also verified that the forced overexpression of CHRDL1 and FAM107A showed tumor suppressive activity in LUSC cell lines." (PMID 38188687, 2023). "Nevertheless, the tumor-suppressive function of FAM107A needs to be further studied in other types of malignancies." (PMID 38188687, 2023). "There was a significant reduction in both migration and invasion in tumor cells after knockdown of FAM107A." (PMID 35669436, 2022). "Therefore, FAM107A may be associated with the regulation of the tumor microenvironment." (PMID 35669436, 2022). "Afterwards, we used the GEPIA2 tool to obtain top 300 FAM107A-correlated genes by combining all tumor expression data of TCGA." (PMID 35669436, 2022). "Although the expression of FAM107A mRNA was observed downregulation in multiple cancers, studies show dual effects of “tumor suppression” and “tumor promotion” of FAM107A in the process of tumor genesis and development." (PMID 35669436, 2022). "A number of studies have confirmed that FAM107A is involved in the process of tumorigenesis and tumor progression in some specific tumor types." (PMID 35669436, 2022). "The results suggest a significant promotion of proliferation rates in the tumor cells with FAM107A downregulation." (PMID 35669436, 2022). "Four kinds of FAM107A genetic alteration were detected from all TCGA tumor samples with a total frequency of about 0.9%, including deep deletion, amplification, missense mutation, and splice mutation." (PMID 35669436, 2022). "Given that tumor-infiltrating immune cells participate in the initiation and progression of cancer, we agreed to explore the potential relationship between FAM107A gene expression and the infiltration level of different immune cells in diverse cancers of TCGA." (PMID 35669436, 2022). "Family with sequence similarity 107, member A(FAM107A) was supposed as a tumor suppressor for various types of tumors." (PMID 35669436, 2022). "Then, we evaluated the differential expression levels of FAM107A mRNA between tumor and normal tissues in the Oncomine and TCGA databases." (PMID 35669436, 2022). "The expression of MMP-9 was also found to decrease after FAM107A overexpression, suggesting that FAM107A overexpression reduces tumor aggressiveness." (PMID 36010909, 2022). "In the present study, the expression level of FAM107A in normal tissues and tumor cell lines was analyzed via HPA, GTEx, and CCLE datasets." (PMID 35669436, 2022).
tumor (continued). "Compared with tumor tissue, we found that all hub genes were significantly higher expressed in dysplasia tissue; except for FAM107A with AUC = 0.66, the other 5 hub genes have AUC > 0.7." (PMID 33376725, 2020). "But it should be emphasized, that in our study group, the primary samples originated predominantly from patients with advanced tumor stage, thus if FAM107A silencing took place at early stage of carcinogenesis, we were not able to observe such association." (PMID 28710449, 2017). "Two potential targets of this asRNA, FAM3D and FAM107A, were also downregulated in TCGA tumours (77.1 and 25.8-fold, respectively)." (PMID 29263803, 2016). "The forced expression of FAM107A was shown to suppress tumor cell proliferation and induce apoptosis." (PMID 24748967, 2014). "Notably, overexpression of FAM107A has been shown to inhibit tumor cell motility, invasion, and proliferation while promoting apoptosis, primarily through modulation of the focal adhesion kinase (FAK)/PI3K/AKT signaling pathway." (PMID 40034825, 2025). "Together, these data strongly suggest that CHRDL1 and FAM107A may act as tumor suppressors in LUSC cells." (PMID 38188687, 2023). "Furthermore, FAM107A overexpression has been shown to act as an inhibitor of tumor growth and invasion in bladder cancer." (PMID 36010909, 2022). "Moreover, the potential correlation of FAM107A genetic alteration with the survival prognosis of different tumor cases was explored using the “Comparison” module of cBioPortal tool." (PMID 35669436, 2022). "Furthermore, the expression of FAM107A in PCa tissues was detected by Western blotting, and the results indicate that the expression of FAM107A in tumor tissues was lower than that in normal prostate tissue." (PMID 36010909, 2022). "In addition, we found statistical correlations of FAM107A expression with DNA methylation, immune cell infiltration, immune checkpoints, and tumor purity." (PMID 35669436, 2022). "On the contrary, FAM107A demonstrated low expression in most tumor cell lines." (PMID 35669436, 2022). "Thus, FAM107A was considered as a tumor suppressor gene due to its decreased expression in various types of cancer and since inducing FAM107A expression suppresses cancer cell proliferation and induces apoptosis." (PMID 24748967, 2014). "HITS may be considered as a candidate tumor suppressor gene, since loss of HITS expression was commonly observed in cancers of various organs, resulting in tumor development and proliferation, similar to FAM107A." (PMID 24748967, 2014). "FAM107A may influence tumor progression by blocking the FAK/PI3K/AKT signaling cascade." (PMID 36010909, 2022). "All results above suggest that FAM107A might serve as a novel anti-oncogene in these tumor types." (PMID 35669436, 2022). "The convergence of tumor suppression (FHIT, FAM107A), metabolic reprogramming (PDHB), and immune/signaling (PTPRG, FAM3D) genes within a single genomic region suggests a potential resistance-associated haplotype block." (PMID 42302616, 2026). "To verify the tumor-suppressive functions of the candidate hub genes, we selected CHRDL1 and FAM107A genes which showed the strongest downregulation in the LUSC samples." (PMID 38188687, 2023). "Our study identified commonly downregulated genes in two cohorts of LUSC datasets, and verified the tumor-suppressive functions of two hub genes in the PPI network (CHRDL1 and FAM107A)." (PMID 38188687, 2023). "To identify the differential expression of FAM107A gene between tumor and normal tissues, we firstly applied the TIMER2 approach to analyze the significance of FAM107A expression." (PMID 35669436, 2022). "According to our findings, the overexpression of FAM107A elevated E-cadherin expression, reduced N-cadherin and vimentin expression, and interfered with EMT in tumor cells." (PMID 36010909, 2022).
tumor (continued). "Likewise, the result showed that “developmental cell growth”, “cell-cell adhesion via plasma-membrane adhesion” and “positive regulation of cAMP mediated signaling” were enriched in GO terms and might be in involved in the impact of FAM107A on tumor pathogenesis." (PMID 35669436, 2022). "On the contrary, two bands, specific for both, FAM107A and GAPDH genes were visible in all applied non-tumor controls (9/9)." (PMID 28710449, 2017). "FAM107A acts as a molecular brake on the FAK/PI3K/AKT pathway, and its reactivation could inhibit tumor growth and metastasis, offering a potential therapeutic target." (PMID 40034825, 2025). "The tumor-suppressive functions of CHRDL1 and FAM107A were validated in two LUSC cell lines." (PMID 38188687, 2023). "In addition, except for PACSIN1 (P > 0.05), the expression levels of FAM107A (P < 0.05) and PTGDS (P < 0.05) were significantly different between tumour and normal samples." (PMID 37325056, 2023). "To be comprehensive, we also combined the HPA, GTEx, and CCLE datasets to assess the expression level of FAM107A in nontumor tissues and various tumor cell lines." (PMID 35669436, 2022). "Therefore, we used the SangerBox tool to investigate the correlation of FAM107A expression with Stromal, Immune, and ESTIMATE score in pan-cancers, which represented the abundance of stromal components, immune components, and tumor purity to some extent." (PMID 35669436, 2022). "Our study confirmed lack of relationship between tumor extension, nodal involvement and tumor differentiation with FAM107A hypermethylation." (PMID 28710449, 2017). "Mechanistically, overexpression of FAM107A inhibits tumor cell proliferation, migration, invasion and promotes apoptosis through the FAK/PI3K/AKT signaling pathway, indicating that FAM107A may be a molecular brake of FAK/PI3K/AKT signaling, thus limiting the active state of the FAK/PI3K/AKT pathway." (PMID 36010909, 2022). "Therefore, we report the recurrent inactivation of FAM107A in LSCC, what may suggest that the gene is a promising tumor suppressor candidate involved in LSCC development." (PMID 28710449, 2017). "We found that the mean methylation level of ITM2A, GALNTL1, FAM107A, and MFAP4 was significantly higher in tumor tissue while the methylation level of PGM5 was higher in normal tissue." (PMID 33376725, 2020). "The FAM107A immunostaining revealed lack of the protein expression in all analyzed primary LSCC samples (15/15; 100%), while in all non-tumor controls (5/5; 100%) nuclear/cytoplasmic FAM107A protein expression was found." (PMID 28710449, 2017).
cancer (16 papers, 2009 to 2023). A tumor composed of atypical neoplastic, often pleomorphic cells that invade other tissues. "All these survival data presented a different association of FAM107A expression with the prognosis of different cancer cases." (PMID 35669436, 2022). "The results displayed that down-regulated FAM107A expression was associated with poor prognosis in many cancers." (PMID 35669436, 2022). "In general, FAM107A is closely associated with cancer development, but how FAM107A affects PCa remains unclear." (PMID 36010909, 2022). "Transcripts of several genes that act as growth inhibitors were less abundant in MtrBTN2, as often seen in cancer contexts, such as FAM107A and LTBP3, which keeps TGF-β in a latent state." (PMID 37816387, 2023). "Further analysis showed that the expression of FAM107A was significantly negatively correlated with TMB in 15 cancer types and MSI in 10 cancer types." (PMID 35669436, 2022). "These implied that the dysregulated expression of FAM107A was mainly influenced by promoter methylation in cancers." (PMID 35669436, 2022). "Nevertheless, it is necessary to perform a pan-cancer analysis to clarify the molecular characteristics and potential role of FAM107A gene in cancers." (PMID 35669436, 2022). "Taken together, our pan-cancer analyses of FAM107A confirmed the expression pattern and prognostic value across multiple cancers." (PMID 35669436, 2022). "Subsequently, the expression status of FAM107A across various cancer types of TCGA was analyzed using the Oncomine dataset." (PMID 35669436, 2022). "Several studies indicated that FAM107A expression is downregulated in various types of cancer, such as non-small-cell lung, renal cell and prostate cancers and astrocytoma by epigenetic silencing, including promoter hypermethylation." (PMID 24748967, 2014). "FAM107A has been consistently reported to be downregulated in human cancer; that conforms to our rules." (PMID 19874631, 2009). "We then used the cBioPortal tool to study the genetic alteration of FAM107A in cancers." (PMID 35669436, 2022). "In addition, FAM107A knockdown promoted the proliferation, migration, and invasion of the cancer cell lines." (PMID 35669436, 2022). "Therefore, we conducted a FAM107A-related pan-cancer analysis across thirty-three tumors based on TCGA database to explore the molecular characteristics of FAM107A." (PMID 35669436, 2022). "Furthermore, a higher DNA methylation level of FAM107A was demonstrated in numerous cancers compared with adjacent tissues." (PMID 35669436, 2022). "Moreover, we further assessed the expression correlations between FAM107A and immune checkpoints in pan-cancers." (PMID 35669436, 2022). "Moreover, correlation analysis showed the expression of FAM107A was correlated with immune checkpoints in diverse cancers with statistical significance." (PMID 35669436, 2022). "Interestingly, we identified “Cell adhesion” and “cAMP signaling pathway” terms as the potential impact of FAM107A on the etiology or pathogenesis of cancers both in GO and KEGG analyses." (PMID 35669436, 2022). "The results indicated that FAM107A might be a vital factor which could influence or predict the response of cancer patients to immunotherapy." (PMID 35669436, 2022). "To identify whether DNA methylation plays an essential role in regulating the gene expression of FAM107A, we firstly applied the GSCALite database to analyze the correlation between DNA methylation of FAM107A and expression in various cancers." (PMID 35669436, 2022). "In addition, the expression of FAM107A was influenced by some non-coding RNAs in cancer." (PMID 35669436, 2022).
cancer (continued). "FAM107A (also known as downregulated in renal cell carcinoma 1 [DRR1]) is a novel unique protein family that exhibits functional similarity with heat shock proteins (HSPs) during the cellular stress response with diverse functions in cancer and the nervous system." (PMID 33804473, 2021). "Thus, the physiological roles and functions of FAM107A in cancer remain controversial." (PMID 24748967, 2014). "FAM107A, which suppresses cell growth, may play a role in cancer development." (PMID 21060876, 2010). "Also, FAM107A may affect the progression of cancer through AKT or NF-κB pathway." (PMID 35669436, 2022). "As for the expression of FAM107A protein, the CPTAC dataset was implemented to explore the difference between primary cancers and normal tissues." (PMID 35669436, 2022). "The expression of FAM107A and FAM107B proteins is prominent in neural cells, whereas their expression is downregulated in cancer cells." (PMID 24748967, 2014). "Analysis of DNA methylation of the FAM107A gene showed a negative correlation between FAM107A expression and promoter methylation in numerous cancers." (PMID 35669436, 2022). "The result showed a negative correlation between FAM107A expression and promoter methylation in various cancers." (PMID 35669436, 2022). "With respect to the genes having interaction(s) with miRNAs, we realized four down-regulated vDEGs (TMEM100, MYH11, CHRDL1, and FAM107A) to the accompaniment of five up-regulated vDEGs (KLK10, CLDN1, SLC6A6, MMP11, and SLC7A5) being documented by the GEPIA in both COAD and READ cancer types." (PMID 35333898, 2022). "Although this resemblance served the purpose of properly separating cancer cell types, mesenchymal cancer cells lack expression of important tRG genes such as AQP4, FAM107A, SOX9, and GLI3, and tRG lack the expression of mesenchymal genes such as CD44 and TIMP1." (PMID 32641768, 2020). "As a result, a statistically negative correlation was observed in various cancers between FAM107A gene expression and the infiltration level of MDSCs, which was supposed to be a risk factor to the prognosis of cancer patients according to the results of survival analysis." (PMID 35669436, 2022).
psychiatric disorder (3 papers, 2014 to 2026). A disorder characterized by behavioral and/or psychological abnormalities, often accompanied by physical symptoms. "Acute stress did not affect expression of hemoglobin genes but it altered expression of Fam107a (Drr1) and Agxt2l1 (Etnppl) that have been implicated in psychiatric diseases." (PMID 25472829, 2014). "FAM107A may be associated with certain types of human psychiatric disorders." (PMID 24748967, 2014). "Although there is currently no direct evidence, FAM107A may be a candidate gene associated with these psychiatric disorders." (PMID 24748967, 2014).
FAM107A also shares sentences with these, for which no sentence is quoted: schizophrenia (5 papers); breast carcinoma (3); melanoma (2); Alzheimer disease (1); brain cancer (1); brain disorder (1); cervical cancer (1); Cognitive impairment (1); colon cancer (1); colorectal cancer (1); esophageal cancer (1); fibrosarcoma (1); head and neck cancer (1); hepatocellular carcinoma (1); Huntington disease (1); kidney cancer (1); malignant glioma (1); mesothelioma (1); neurodegenerative disease (1); neurological diseases (1); ovarian carcinoma (1); pancreatic adenocarcinoma (1); pancreatic cancer (1); Pheochromocytoma and Paraganglioma (1); sarcoma (1); testicular cancer (1); uterine carcinosarcoma (1).